PDGFRB (platelet derived growth factor receptor beta)
Diseases named in the same sentence as PDGFRB in open-access papers (continued):
Sharing a sentence is not in itself a finding about the gene and the disease.
tumor (continued). "Comparable to primary tumor cell lines, CRISPR/Cas9 knock-out of PDGFRβ in ALK+ cells also led to a decrease in proliferation when seeded at a low cell density." (PMID 36045346, 2022). "The Ate-Grab-treated group, which exhibited decreased tumor fibrosis, had greater NG2+ or PDGFRβ+ pericyte coverage." (PMID 36272973, 2022). "In a transgenic mouse model that mimics PDGFRβ-driven human ALCL in vivo, we identify PDGFRβ as a driver of aggressive tumor growth." (PMID 36045346, 2022). "Pericyte-1 was enriched in the tumor fraction and characterized by higher expression of genes related to a pro-inflammatory capillary phenotype (RGS5, KCNJ8, AXL, ABCC9, PDGFRB, and THY1)." (PMID 36180422, 2022). "PDGFRβ activation then leads to ECM remodeling, including TNC upregulation, and promotes CAF migration and CAF-induced tumor cell invasion." (PMID 36003785, 2022). "We show here that T cell-specific deletion of PDGFRβ in a genetically engineered mouse model mimicking human ALCL in vivo, leads to delayed tumor growth and prolonged survival." (PMID 36045346, 2022). "The activation of the cell surface protein kinases PDGFRA, PDGFRB and EGFR promotes cell proliferation in normal cells and is enhanced in certain tumour types, while their down-regulation is in accord with the cell cycle inhibition we uncovered." (PMID 35205253, 2022). "During the differential gene expression analysis of diosgenin-regulated genes, we observed that PDGFRB, FBFR2, and STAT3 possess maximum gene expression in tumor and metastatic vs." (PMID 36686654, 2022). "Vascular endothelial growth factor receptor 2 (VEGFR2), platelet-derived growth factor receptor beta (PDGFR-β) and v-kit cellular homologue (c-KIT) are receptor tyrosine kinases (RTK), whose expression has been reported in multiple canine tumours." (PMID 35324835, 2022). "MBP-11901, a multi-RTK inhibitor, was shown to inhibit tumor growth and kill HCC by targeting VEGFR2, c-KIT, PDGFRβ, and FLT3." (PMID 35454900, 2022). "Encouraged by the success of FAPI-PET, we set out to study the potential value of PDGFRB-targeted molecular imaging for the detection of peritoneal metastases and, potentially, other CMS4-like stroma-rich tumour types." (PMID 36139509, 2022). "Sorafenib inhibits angiogenesis and tumour progression by limiting the effects of various receptor tyrosine kinases such as VEGFR-2, VEGFR-3, c-KIT, or platelet-derived growth factor receptor beta (PDGFRβ)." (PMID 35954446, 2022). "PDGFRα is a marker for fibroblasts in some tissues like skin, whereas PDGFRβ is expressed in fibroblasts, pericytes, and CAFS in multiple tissues and tumour types." (PMID 36555218, 2022). "Sorafenib blocks tumor angiogenesis by targeting vascular endothelial growth factor receptor-2/-3 (VEGFR-2/-3) and platelet-derived growth factor receptor-beta (PDGFR-beta) tyrosine kinases." (PMID 36483039, 2022). "On the other hand, whereas PDGFRB expression was only seen in 22% of normal glial cells, in GBM tumours its expression was increased and detectable in 65%." (PMID 33478100, 2021). "Transcript for PDGFRa, PDGFRb, VEGFR2, and KIT was detectable in all of the primary UC tumor samples and UC cell lines although this was present at varying degrees." (PMID 34600548, 2021). "Tumor expression of TGFBI, IGFBP3, and CHI3L1 were positively correlated with PDGFD and PDGFRB expression in TCGA LGG dataset, respectively." (PMID 34539622, 2021). "We observed that in the primary tumor samples evaluated, the profile of RTK activation in UC cells lines was similar to that found in tumors with evidence of PDGFRα and PDGFRβ phosphorylation present in only 25% of UC cell lines evaluated." (PMID 34600548, 2021). "In particular, Sorafenib interacts with BRAF, BRAFV600E, cKIT, and FLT3 on tumor cells and VEGFR2–3 and PDGFRβ on tumor endothelial cells." (PMID 34205656, 2021).
tumor (continued). "Potential prognostic and predictive effects of stromal PDGFRb expression in the primary tumor could be mediated by paracrine acting factors released by the microenvironment which act directly or indirectly on the tumor to promote progression and render tumor cells insensitive to RT." (PMID 33661437, 2021). "Our data using ten fresh-frozen tumor samples showed that in all GCTB tissues, there was similarly high relative phosphorylation of M-CSFR, InsR and PDGFRβ, as well as CREB and ERK1/2, independent of the treatment." (PMID 34298757, 2021). "Therefore, whether PDGFRβ/PDGF-BB axis is invovled in the initial recruitment of resident CD90+CD73+ cells to growing tumors requires further investigation in a well-defined murine tumour model." (PMID 34740105, 2021). "Preclinical studies have shown that the combination of Dasatinib and cisplatin, a combination of Src, c-kit, and PDGFRβ, can inhibit the growth of basal-like tumor cells or TNBC tumor cells." (PMID 34198652, 2021). "Real time PCR was performed to provide an initial assessment of mRNA transcript expression of the RTKs PDGFRa, PDGFRb, VEGFR2, and KIT in primary UC tumor samples (N = 9) and established canine UC cell lines (N = 5)." (PMID 34600548, 2021). "Consistent with the current study, in MPM, PDGFRB is expressed in both stromal fibroblasts and MPM tumor cells." (PMID 33955203, 2021). "This is in accordance with its function as tumour suppressor in GBM by negatively regulating epidermal growth factor receptor (EGFR) and platelet-derived growth factor receptor beta (PDGFRB) genes." (PMID 33610185, 2021). "While transcript for PDGFRα, PDGFRβ, VEGFR2 and KIT was detected in all tumor samples and UC cell lines, the pattern of expression was variable." (PMID 34600548, 2021). "Here, TGFβ1 upregulates PDGFRβ expression in peritumoral CD90+CD73+ cells, which is invovled in the recruitment of pericytes to growing tumours via tumor-derived PDGF-BB." (PMID 34740105, 2021). "In SCG, the primary tumor site was correlated with expression levels of PDGFB and PDGFRB (P < 0.05)." (PMID 33524869, 2021). "Analysing 128 murine tumours, we identified 5–6 main CAF populations and numerous minor ones based on the analysis of αSMA, FAPα, PDGFRα, PDGFRβ, CD26, and PDPN." (PMID 34016130, 2021). "This study showed that PDGFRβ was overexpressed and that THBS4 was significantly increased in the tumor tissue when compared to normal colon tissue in CRC patients." (PMID 32899998, 2020). "Although we did not observe a significant difference in MYC (p = 0.08) or LPL (p = 0.11) expression between basal-TNBC and CL-TNBC, we did find that CL-TNBC tumours had significantly higher expression of CD36 (p < 0.0001) and PDGFRB (p < 0.0001)." (PMID 31942031, 2020). "To further investigate the identity of the cells expressing TSPO in the tumor microenvironment, we performed immunofluorescent co-staining against CD31 and PDGFRB." (PMID 31963507, 2020). "Inhibition of TGFβ signaling in tumor cells significantly decreases PDGFRβ expression and PDGF-stimulated tumor cell invasion, which indicates the possibility of downstream TGFβ signaling." (PMID 32899998, 2020). "To confirm its expression profiles in the OSCC tumor microenvironment, we isolated tumor infiltrating immune cells (TILs) and CAFs using CD45 and PDGFRb antibodies by flow cytometry." (PMID 33204328, 2020). "Platelet-derived growth factor receptor β (PDGFRβ) is highly expressed in invasive TNBC, both on tumor cells and tumor microenvironment." (PMID 32892748, 2020). "Although the role of the PDGFB/PDGFRB axis in BC progression is still a subject of debate, PDGFRB overexpression was correlated with the acquisition of vascular-like functional properties of TNBC, suggesting its involvement in tumor aggressiveness." (PMID 32143514, 2020). "We recently proved that tumor growth and lung metastases are impaired in mouse models of human TNBC by a high efficacious PDGFRβ aptamer." (PMID 32892748, 2020).
tumor (continued). "It is plausible that 1-NaPP1 directly inhibits bone marrow PDGFRβ-positive progenitor cells, thereby preventing their differentiation into NG2-positive pericytes and PDGF-BB-induced pericyte recruitment to the tumor." (PMID 31938055, 2020). "Co-inhibition of PDGFRβ by AG1295, an inhibitor of PDGFR, with erlotinib effectively suppressed tumor growth." (PMID 31284441, 2019). "Cumulatively, our data suggests that PDGFRβ inhibition can evade the resistance to a combined MEK1/2-JAK2 inhibition and can enhance tumor suppression in immunocompetent mice." (PMID 30777101, 2019). "Validation of these findings in patient samples of skin SCCs shows a strong correlation between the expression of SDF1, PDGFRA, and PDGFRB, which is upregulated, along CXCR4 in tumor cells of advanced SCCs." (PMID 30874597, 2019). "Several receptors have already been explored for this approach, namely CD13, CD276, Extra domains of fibronectin (A, B), Integrin αvβ3, Neuropilin-1, Nucleolin, PDGFRβ, tissue factor, and VEGFR-2, which are overexpressed on tumor vasculature." (PMID 33568892, 2019). "The phosphorylation levels of Insulin Rβ (Tyr1150/1151), PDGFRβ (Tyr751), VEGFR2 (Tyr996), and HGFR (Met Tyr1234/1235) were found to be increased in the tumor tissues in comparison to the paired adjacent tissues." (PMID 31690270, 2019). "Forty-one (8%) of primary tumours displayed a high expression of both PDGFRα in tumour cells and PDGF-CC, 63 (13%) of PDGFRα in stromal cells and PDGF-CC, and 36 (7%) of PDGFRβ in stromal cells and PDGF-CC." (PMID 29380207, 2018). "In contrast, more than half of the tumours with high PDGF-CC and high PDGFRα expression in tumour or stromal cells displayed low PDGFRβ." (PMID 29380207, 2018). "Accordingly, the anti-PDGFRβ 2′F-Py-RNA Gint4.T aptamer was able to target PDGFRβ-positive GBM either subcutaneously or intracranially implanted in mice, acting as inhibitor of tumor growth and delivery agent for drug-loaded nanoparticles." (PMID 30428522, 2018). "Our evidence suggests that Dll4/Notch signaling amplification stabilizes tumor vessels by enhancing EphrinB2/EphB4 and PDGF/ PDGFRβ signaling and, therefore, promoting vascular maturation." (PMID 28288569, 2017). "Both tumours demonstrate positivity for CD146 and PDGFRβ, supporting the idea that they are pericyte-derived tumours." (PMID 27916653, 2017). "Thus, it should be hypothesized that the tumor progression in MPM is driven by PDGFRB over-expression rather than its activating mutations." (PMID 28435517, 2017). "The decision to include sunitinib and vorinostat was based on our findings that PDGFRB and HDAC3/8 were overexpressed in our patient's tumor." (PMID 28993730, 2017). "These tumours showed similar patterns of immunoreactivityto tumours obtained from whole sphere populations when stained with antibodies against PMEL, SMA, PDGFRβ, CATHEPSIN K, NG2 and S100, as well as displayed E-CADHERIN positive epithelial structures." (PMID 29133867, 2017). "Both PDGFRβ and VEGFR2 are expressed in epithelial tumor cells as well as stromal and endothelial cells." (PMID 29228656, 2017). "These tumours expressed the AML marker proteins HMB45, SMA, VIMENTIN, PDGFRβ and epithelial structures were positive for E-CADHERIN." (PMID 29133867, 2017). "PDGFB and PDGFRB are less expressed relatively to PDGFC in perinecrotic zone, and also in comparison to PDGFRA in cellular tumour block." (PMID 29127351, 2017). "To assess the expression and tissue localization of PDGFRβ in OSCC, we performed immunostaining in twelve OSCC tumor tongue specimens and paired morphologically normal AE tissue." (PMID 27128408, 2016). "In this tumor, the fusion protein is processed into a functional PDGFBB leading to an autocrine activation of PDGFRβ which is recognized as driver of the oncogenic transformation." (PMID 27374103, 2016).
tumor (continued). "Perivascular cells expressing PDGFRβ, a mesenchymal marker of ASC40, 49, were significantly less abundant in CXCL1-sh-RM1 tumours compared with control-sh-RM1 tumours." (PMID 27241286, 2016). "Immunohistochemical analysis of tumor tissue demonstrated upregulation of NG2, Ki67 (proliferation marker), PDGFRα, PDGFRβ and GFAP." (PMID 25987129, 2015). "Based on the expression and the activation status of PDGFRβ in CSC, documented by our and other groups, sunitinib likely exerts a direct inhibition of the PDGFRβ-driven pathway in the tumor cells of the patient here studied." (PMID 25880253, 2015). "Two tumor-homing peptides were investigated for targeting purposes, p15-RGR and p46-RGD, both containing a polyhistidine-tag on their N-terminus, targeting PDGFRβ and αv-integrins, respectively." (PMID 25126543, 2014). "PDGFRβ is a single transmembrane glycoprotein and a member of the type III protein tyrosine kinase family, which plays an important role in tumor cell proliferation and angiogenesis." (PMID 24649266, 2013). "Thus, paradoxical up-regulation of PDGFRβ may impair anti-tumor activity of rapamycin in HCC." (PMID 22428038, 2012). "Cytoplasmic PDGFRβ expression was noted in 4/24 primary and 1/10 metastatic AGASACA and 4/15 TC tumor cells, while intense stromal staining was noted in all tumor samples." (PMID 22630170, 2012). "Using siRNA mediated knockdown of PDGFRβ, we confirmed that subsequent activation of AKT and ERK was PDGFRβ-dependent and compromised the anti-tumor activity of rapamycin." (PMID 22428038, 2012). "To distinguish between these possibilities we stained frozen tumor sections with nestin, MAP2, PDGFRβ, and β-catenin specific antibodies." (PMID 22891161, 2012). "As a multikinase inhibitor, sorafenib has shown anti-tumor activity by decreasing ERK and PDGFRβ activation, as well as AKT phosphorylation in a group of human malignancies." (PMID 22428038, 2012). "While the messages for VEGFR2, Kit, PDGFRα and PDGFRβ were detected in all tumor samples, only PDGFR-α and VEGFR2 expression were detected in all AGASACA and TC tumor cells by IHC." (PMID 22630170, 2012). "Consistent with the in vivo findings, tumor cells expressing low levels of IGF-IR (RJ348 and RJ423) expressed high levels of PDGFRα and PDGFRβ compared to the RJ345 cells." (PMID 22070644, 2011). "Although there was some inter-tumor variability, the IGF-IR-independent recurrent spindle tumors displayed an overall increase in both PDGFRα and PDGFRβ, with some tumors displaying especially high levels." (PMID 22070644, 2011). "The inhibition in tumor growth was therefore probably due to the inhibition of the three established targets (VEGFR1, VEGFR3, and PDGFRβ), leading to the inactivation of alternative pathways to the ERK pathway and, subsequently, to a decrease in tumor growth." (PMID 21998674, 2011). "The other target genes, FLT3, CSF1R, PDGFRB, AXL and MET showed lower expression levels in the tumor tissue compared to normal tissue except AXL in NF1 associated GIST." (PMID 21171987, 2010). "Mechanistically, these observations align with bioinformatic analyses highlighting PDGFRβ as an upstream regulator of multiple downstream effectors—PPARγ, VEGFA, ANG-2, VIM, COL1A1, and Cadherins all integral to tumor progression, angiogenesis, and cellular plasticity." (PMID 40282535, 2025). "Non-tumor components included endothelial cells (expressing VWF, CDH5, ECSCR, SLCO2A1, and MYCT1), pericytes (marked by RGS5, MCAM, and PDGFRB), normal oligodendrocytes (showing PTGDS, MBP, TF, and MOG expression), and TAMs (identified by CD14, AIF1, FCER1G, FCGR3A, TYROBP, and CSF1R)." (PMID 41394801, 2025). "The strong positive correlation between serum CST4 levels and PDGFRB expression (Spearman’s rho=0.42, P<0.001) suggests a coordinated regulatory mechanism that may drive extracellular matrix (ECM) remodeling and tumor vascularization." (PMID 41040534, 2025).
tumor (continued). "Separately, a mechanistic study using the Cancer Genome Atlas (TCGA) data and breast cancer models demonstrated that PDGFRβ, along with caveolin-1 (Cav-1), promotes autophagy in CAFs through the mTOR/FIP200/ATG13 pathway and enhances tumor invasiveness via HIF-1α/MCT4/MCT1 signaling." (PMID 41441395, 2025). "The statistical analysis did not reveal significant differences in PDGFRβ expression among tumor histotypes, likely due to the limited number of cases per group." (PMID 41472102, 2025). "Next-generation sequencing results showed PDGFRB D850V, tumor mutation burden (TMB) was not high, microsatellite was stable, and tumor proportion score (TPS) was 25%." (PMID 41209976, 2025). "The cell type-specific markers we used for cell annotation were as follows: T cell (CD3D); NK cell (KLRD1 and NKG7); plasma cell (IGKC and JCHAIN); Mast cell (KIT and TPSB2); tumour cell (CA9, NDUFA4L2 and SLC17A3); endothelium (PECAM1, PTPRB and KDR); mesangial cell (ACTA2 and PDGFRB)." (PMID 40830065, 2025). "Regorafenib is a sorafenib-derived multi-kinase inhibitor that targets tumor cells and their microenvironment due to inhibition of angiogenic (VEGFR1-2 and TIE-2), stromal (PDGFRβ and FGFR1), oncogenic (RET and c-KIT), and intracellular (BRAF, c-RAF/Raf-1) kinases." (PMID 41154409, 2025). "Experiments using the hypomorphic PDGFB-ret/ret mouse model, which expresses a truncated form of PDGF-B, lacking the C-terminal retention motif, resulted in impaired tumor angiogenesis and reduced pericyte coverage implying PDGF-BB/PDGFRβ as a promising, potential therapeutical target." (PMID 38980580, 2024). "Elevated histone lactylation levels have also been reported in lung cancer cells, renal cancer cells, and melanoma cells to promote tumor occurrence and development through mediating HK-1 and IDH3G gene expression, or transcriptionally activating the expression of PDGFRβ and YTHDF2." (PMID 38200523, 2024). "Tested in both preventive and therapeutic settings across murine colon, lung, and breast cancer models, the vaccine induced cell-specific lysis of PDGFRβ-expressing tumor cells without affecting non-expressing cells." (PMID 39081320, 2024). "The collaborative signaling among EGFR, PDGFRα, PDGFRβ, and FGFR2 proteins could result in a synergistic effect on promoting tumor progression making them valuable targets for cancer therapy." (PMID 38338684, 2024). "Although PDGFRβ expression in KO mice was significantly decreased at 12 weeks old, the difference disappeared in both tumor and non-tumor areas at 20 weeks of age." (PMID 39394459, 2024). "Moreover, 94% (15/16), showed high expression of PDGFRβ, 88% (14/16) exhibited the presence of PDGFRa, and 81% (13/16) showed similar expression in the tumor stroma, while high CD24 expression in the tumor was observed in 63% of cases (10/16)." (PMID 38791897, 2024). "Importantly, ADAMTSL5 confers tumorigenicity by upregulating oncogenic inputs (i.e., MET, EGFR, PDGFRβ, IGF1Rβ, FGFR4), and its abrogation increases sensitivity of tumor cells to clinically relevant drugs." (PMID 38495872, 2024). "Fibroblast activation markers FAP, CD29, αSMA, PDPN, CD90, FSP1 and PDGFRβ expression levels were determined and compared for tumour and non-cancerous adjacent lung tissue from NSCLC patients by looking at the percentage positivity for each marker." (PMID 38582812, 2024). "In order to specifically address Iren-AuSiO2_COOH to target tumor/stromal cells, conjugation with the EGFR CL4 (Iren-AuSiO2_CL4) or PDGFRβ Gint4.T (Iren-AuSiO2_Gint4.T) aptamers, and dual functionalization with both CL4 and Gint4.T (Iren-AuSiO2_CL4_Gint4.T) were performed." (PMID 38532439, 2024). "In premenopausal patients (n = 11), six genes were statistically significantly down-regulated in tumour tissue compared to tumour-adjacent tissue: TIMP3 (13.1-fold), ENPP2 (11.4-fold), FGF2 (7.6-fold), CXCL12 (7.5-fold), TIMP2 (5.2-fold), and PDGFRB (4.9-fold change)." (PMID 37509322, 2023).